AKR1C2 (aldo-keto reductase family 1 member C2)
Diseases named in the same sentence as AKR1C2 in open-access papers (continued):
Sharing a sentence is not in itself a finding about the gene and the disease.
melanoma (4 papers, 2019 to 2025). A malignant, usually aggressive tumor composed of atypical, neoplastic melanocytes. "Specifically, they noted that the overexpression of BRD4, a member of BET family, upregulated a metabolic enzyme, called Aldo-Keto Reductase family 1 member C2 (AKR1C2), in melanoma cells." (PMID 41339932, 2025). "Recent studies suggested that aldo-keto reductases (AKRs), a superfamily of NADPH-linked oxidoreductases, including AKR1C1, AKR1C2, and AKR1C3, are potential NFE2L2 target genes responsible for ferroptosis resistance via inhibiting lipid peroxidation in melanoma cells." (PMID 34938739, 2021). "Furthermore, it has been demonstrated that in melanoma, BET inhibitors enhance GPX4 inhibition-induced ferroptosis through dual downregulation of AKR1C2." (PMID 40531841, 2025). "Consistently, inhibition of AKR1C2 sensitized melanoma cells to ferroptosis and the genetic inhibition of BRD4 enhanced the ferroptosis induced by RSL3 suggesting that BET inhibitors sensitize melanoma cells to ferroptosis." (PMID 41339932, 2025).
Alzheimer disease (3 papers, 2020 to 2025). A progressive, neurodegenerative disease characterized by loss of function and death of nerve cells in several areas of the brain leading to loss of cognitive function such as memory and language. "Another protein found exclusively on the CMD membrane was Aldo-keto reductase 1C2 (AKR1C2) shown previously to be increased in the late stages of Alzheimers Disease." (PMID 32728348, 2020). "Dysregulation of AKR1C2 and AKR1C3 has been observed in Alzheimer’s disease, suggesting their potential role in disease progression." (PMID 37965040, 2023).
liver cancer (3 papers, 2017 to 2025). An epithelial or non-epithelial malignant neoplasm that arises from the liver. "AKR1C2 induces chemotherapy resistance in bladder, lung, and gynecological cancers and enhances the invasive and metastatic potential in esophageal and liver cancers." (PMID 40361399, 2025).
Abdominal obesity (2 papers, 2018 to 2021). Excessive fat around the stomach and abdomen. "AKR1C2 is known to be associated with central obesity and association with long-term weight gain in men has been suggested." (PMID 30380678, 2018). "We hypothesized that increased AKR1C2 expression is associated with abdominal obesity and that analysis of genetic variants in key regulatory elements suggests putative mechanisms related to possible hormonal control of AKR1C2 expression." (PMID 33675863, 2021).
breast tumor (2 papers, 2014 to 2023). "Furthermore, a high expression of AKR1C1, but not of AKR1C2 had a negative prognostic value in patients with HER2+ early stage breast tumors." (PMID 37469415, 2023).
cervical cancer (2 papers, 2020 to 2021). A primary or metastatic malignant neoplasm involving the cervix. "Overexpression of AKR1C2 is found to be a mildly favorable prognostic marker but lower expression of NADH:ubiquinone oxidoreductase subunit A11 (NDUFA11) is prognostically unfavorable in cervical cancer." (PMID 34790674, 2021). "Our results also showed that the protein expression of MGST3, AKR1C2, and ERLIN1 decreased in cervical cancer cells in the presence of AS-IV." (PMID 32265995, 2020).
colorectal cancer (2 papers, 2020 to 2022). A primary or metastatic malignant neoplasm that affects the colon or rectum. "The expression of selected genes related to MG degradation III (AKR1B10, AKR1C2 and ADH4), glyoxalase system (GLO1 and HAGH), glucose transport (SLC2A1 and SLC5A1) and colorectal cancer-associated genes (AREG, CXCL8 and CEACAM1) were quantitated using qRT-PCR." (PMID 32561807, 2020).
lung adenocarcinoma (2 papers, 2021 to 2025). A carcinoma that arises from the lung and is characterized by the presence of malignant glandular epithelial cells. "AKR1C2 is highly expressed in lung adenocarcinoma tissues, and the expression level correlates with patient gender, tumor stage, lymph node metastasis, and prognosis." (PMID 40531841, 2025). "The expression of AKR1C1, AKR1C2, AKR1C3, and AKR1C4 proteins, which was mainly overexpressed in lung adenocarcinoma (A549) cells and associated with drug resistance in NSCLC, was found in the A549 CD166 + EpCAM + CSC subpopulation." (PMID 33670440, 2021).
non-small cell lung carcinoma (2 papers, 2020 to 2021). A group of at least three distinct histological types of lung cancer, including non-small cell squamous cell carcinoma, adenocarcinoma, and large cell carcinoma. "Moreover, the overexpression of AKR1C1/AKR1C2 may serve as a biomarker of chemoresistance in non-small cell lung cancer cells." (PMID 34778244, 2021).
squamous cell carcinoma (2 papers, 2021 to 2025). A carcinoma arising from squamous epithelial cells. "In squamous cell carcinoma, AKR1C2 has already been shown to be a targetable oncogene." (PMID 39941834, 2025).
acute myeloid leukemia (1 paper, 2023). Acute myeloid leukemia (AML) is a group of neoplasms arising from precursor cells committed to the myeloid cell-line differentiation. "AKR1C2 combined with SOCS1 could exert synergistic effects on predicting the prognosis in patients with acute myeloid leukemia (AML)." (PMID 36701414, 2023).
atopic dermatitis (1 paper, 2026). "Our findings establish a causal relationship between specific gut bacteria (Eubacterium eligens group) and atopic dermatitis risk while identifying seven key bridging genes (AKR1C2, GALE, GGH, NR4A1, PLA2G4B, TYMS) that connect gut microbial metabolites to skin pathology." (PMID 41556698, 2026).
bladder cancer (1 paper, 2014). "The present study demonstrated that induction of AKR1C2 can be found in cisplatin-resistant human bladder cancer cells and contributes to cisplatin drug resistance." (PMID 24527071, 2014). "The function of AKR1C2 in chemoresistance was studied using the human HT1376 bladder cancer cell line and the cisplatin-resistant HT1376-CisR subline." (PMID 24527071, 2014). "In the present study, AKR1C2 expression was identified only in the cisplatin-resistant human bladder cancer cells." (PMID 24527071, 2014). "Further studies are required to validate the practical significance of AKR1C2 in bladder cancer." (PMID 24527071, 2014).
colon cancers (1 paper, 2016). "In colon cancers, studies reported that the up-regulated expression of AKR1B10, AKR1C1, AKR1C2 and AKR1C3 contributed to chemotherapeutic drug resistance indirectly, by reducing oxidative stress generated by these chemotherapeutic agents." (PMID 27635343, 2016).
diabetes (1 paper, 2020). "In the prostate tissue of patients with T2D, AKR1C1 and AKR1C2 transcripts were higher compared to samples of patients without diabetes." (PMID 32932589, 2020). "In the BEN T2D group, we observed higher gene expression level of AKR1C2 than in the group without diabetes." (PMID 32932589, 2020).
glioblastoma (1 paper, 2023). The most malignant astrocytic tumor (WHO grade IV). "In addition, the results showed that AKR1B1, AKR1C2, and AKR1C3, which were also members of the aldosterone reductase family, were also involved in the mechanism of the resistance of glioblastoma to adriamycin." (PMID 37173953, 2023).
hepatoma (1 paper, 2022). "In addition, EXPH1, AKR1C2 and AKRB10 were predominantly expressed in hepatoma cells." (PMID 35967424, 2022).
hyperandrogenism (1 paper, 2025). Excessive secretion of androgens from the adrenal glands or gonads. "We conclude that subcutaneous adipocytes are a site of 5α-DHT inactivation through AKR1C2, and that inhibitors of AKR1C2 could contribute to hyperandrogenism and elevate 5α-DHT levels in an intracrine-dependent manner." (PMID 40421431, 2025). "We have found that perfluorooctanoic acid is a tight binding inhibitor of AKR1C2 and leads to increased 5α-DHT formation, suggesting that this endocrine-disrupting chemical could play a role in hyperandrogenism." (PMID 40421431, 2025).
Hyperglycemia (1 paper, 2020). An increased concentration of glucose in the blood. "Hyperglycemia was indeed found to induce the mRNA levels of AKR1C1, AKR1C2, and AKR1C3." (PMID 32932589, 2020).
lymph node metastasis (1 paper, 2025). "The expression level of AKR1C2 in patients with lymph node metastasis was slightly higher than that in those without lymph node metastasis (P < 0.05)." (PMID 40531841, 2025). "Meanwhile, the correlation analysis and prognostic analysis in this study showed that the expression level of AKR1C2 was closely related to gender, tumor stage, and lymph node metastasis of LUAD patients and that the prognosis of patients with high AKR1C2 expression was worse." (PMID 40531841, 2025).
metastatic prostate carcinoma (1 paper, 2023). A carcinoma that arises from the prostate gland and has spread to other anatomic sites. "The down-regulated expression level of AKR1C2 combined with upregulated expression of SRD5A1 and SRD5A3 may lead to the high levels of DHT either in primary or metastatic prostate cancer." (PMID 36701414, 2023).
neuroblastoma (1 paper, 2023). Neuroblastoma (NB) is the most common solid, extracranial childhood tumor. "A recent study demonstrated that a signature consisting of five genes (AKR1C2, NCAN, AHCY, FBP2 and GALNT3) has potential prognostic values in neuroblastoma." (PMID 36701414, 2023).
oropharyngeal squamous cell carcinoma (1 paper, 2024). "This study provides an analysis of the expression and regulation of Aldo-Keto Reductase 1C2 (AKR1C2) in HPV-positive and HPV-negative oropharyngeal squamous cell carcinoma (OPSCC)." (PMID 39272833, 2024).
prostate tumor (1 paper, 2013). "We however found high expression levels of certain steroidogenic enzymes; SRD5A1, AKR1C2, AKR1C3, and HSD17B10, in bone metastases when compared to non-malignant prostate and primary prostate tumor tissue." (PMID 24244276, 2013).
renal carcinoma (1 paper, 2017). A carcinoma arising from the epithelium of the renal parenchyma or the renal pelvis. "Increased expression of proteins involved in sex steroid inactivation (AKR1C1, AKR1C2, AKR1C3, AKR1B10) in DIO1 re-expressing renal cancer cells might indicate decreased local production of androgens, which have been linked to proliferation of renal and other cancers expressing androgen receptor." (PMID 29272308, 2017).
stomach carcinoma (1 paper, 2014). "Increased mRNA expression of AKR1B1, AKR1C2, and carbonyl reductase (CR) and induction of carbonyl-reducing enzymes AKR1B1 and AKR1C2 can account for drug resistance to some anticancer agents, for instance, the resistance of human stomach carcinoma cells to daunorubicin." (PMID 24648844, 2014).
triple-negative breast carcinoma (1 paper, 2025). An invasive breast carcinoma which is negative for expression of estrogen receptor (ER), progesterone receptor (PR), and human epidermal growth factor receptor 2 (HER2). "Silencing AKR1C2 inhibits triple-negative breast cancer cells’ ability to proliferate, migrate, invade, develop, and spread to the lungs." (PMID 40531841, 2025).
tumor (30 papers, 2009 to 2025). "Moreover, stable downregulation of AKR1C2 can partially rescue the suppression of tumor development caused by siRNA against Ki67 exon 7 in vivo." (PMID 36835286, 2023). "Meanwhile, the results of differential analysis showed that the expression level of the AKR1C2 gene was significantly higher in tumor tissues compared with normal tissues." (PMID 40531841, 2025). "We first used qRT-PCR and Western blot to compare the expression of AKR1C2 in normal lung epithelial cells with that in A549 cells in order to gain a better understanding of the function of AKR1C2 in tumor cells." (PMID 40531841, 2025). "In the GSE19826 dataset, the tumor group’s expression levels of AKR1C2 and KRAS declined compared to the normal group; however, HCAR1 expression levels increased." (PMID 41050072, 2025). "In conclusion, AKR1C2 expression in tumor tissue is sex-dependent and, therefore, has a different predictive value." (PMID 39272833, 2024). "The key findings indicate that increased AKR1C2 expression is significantly associated with positive HPV status and higher AJCC classification, reflecting its potential role in tumor progression." (PMID 39272833, 2024). "RNA-seq revealed that aldo-keto reductase AKR1C2 is a novel tumor-suppressive gene targeted by Ki67 exon 7-included isoform in HNSCC cells." (PMID 36835286, 2023). "To further explore the vital roles of AKR1C2 in immune regulation, we evaluated the correlation between AKR1C2 and tumor-infiltrating immune cells (TIICs) of GC." (PMID 36701414, 2023). "We found that the mRNA expression level of AKR1C2 was correlated with N stage tumor (p = 0.014) and residual tumor (p = 0.025)." (PMID 36701414, 2023). "For example, the expression of two genes (AKR1C1 and AKR1C2) in carcinoma cells and stromal fibroblasts and their positive correlation are favorable tumor characteristics in primary BC patients." (PMID 35617355, 2022). "In tumorous breast tissues the expression of AKR1C1 and AKR1C2 is reduced promoting tumor growth and progression." (PMID 33593445, 2021). "Our previous studies demonstrated that AKR1C2, an isoform of aldo-keto reductase 1C (AKR1C), was frequently detected in PCa patients and was associated with disease status, tumor grade and androgen receptor expression." (PMID 29100377, 2017). "Overexpression of cdk6 in tumor cell lines having low cdk6 resulted in decreased levels of mRNAs encoding aldo-keto reductase (AKR)1C1, AKR1C2 and AKR1C3, which are hydroxysteroid dehydrogenases (HSDs) involved in steroid hormone metabolism." (PMID 24848372, 2014). "The genes of the SLC family such as SLC2A14 and SLC2A3 and the AKR1 (aldo-keto reductase 1) family such as AKR1C1, AKR1C2, AKR1C3 and AKR1B10 were associated with the metabolic processes of tumor cells." (PMID 20003295, 2009). "(B) Expression of AKR1C2 gene in tumor tissues versus normal tissues." (PMID 40531841, 2025). "AKR1C2 gene expression was significantly elevated in tumor tissues (P < 0.001)." (PMID 40531841, 2025). "In addition, women in this cohort showed better overall survival when AKR1C2 expression in tumor tissue was higher than that in men with high AKR1C2 expression." (PMID 39272833, 2024). "Overall, our study suggested a new Ki67/AKR1C2 axis in HNSCC tumor progression." (PMID 36835286, 2023). "AKR1C2 functions as a tumor suppressor during the tumorigenesis of CAL 27 in nude mice." (PMID 36835286, 2023). "Our study suggests a new SRSF3/Ki67/AKR1C2 axis in HNSCC tumor progression." (PMID 36835286, 2023). "Our study also suggested a new SRSF3/Ki67/AKR1C2 regulatory axis during HNSCC tumor progression." (PMID 36835286, 2023). "The knockdown of AKR1C2 could significantly inhibit the in vivo tumour growth while overexpressed AKR1C2 could promote them." (PMID 32678482, 2020). "There have been debates regarding the role of AKR1C2 in tumours." (PMID 32678482, 2020).
tumor (continued). "Statistical results showed that gelsolin expression in PCa was associated with disease status, tumor grade, cigarette smoking, serum PSA level, lymphovascular infiltration and the expression of androgen receptor, AKR1C2 and epidermal growth factor receptor (EGFR)." (PMID 29100377, 2017). "In the TCGA-STAD dataset, AKR1C2 exhibited reduced expression in the tumor group; conversely, HCAR1, KRAS, and PHKG2 showed increased expression in the tumor group." (PMID 41050072, 2025). "In conclusion, our study indicates that AKR1C2 knockdown promotes ferroptosis in LUAD cells and inhibits their proliferation, migration, invasion, and tumor growth." (PMID 40531841, 2025). "As to GCLM and AKR1C2, they are the first-rate limiting enzymes of GSH synthesis and are involved in eliminating ROS and regulating tumor invasion, migration, and other malignant phenotypes." (PMID 41300449, 2025). "AKR1C2 protein expression was correlated with survival outcomes in combination with clinicopathological data such as sex, HPV status, tumor status, smoking history, alcohol consumption, and protein expression levels of AKR1C1, AKR1C3, and NRF2." (PMID 39272833, 2024). "Using the gene list expressed in these hotspots within the high-violence tumor samples, functional enrichment analysis revealed an upregulation of glucocorticoid biosynthesis in AKR1C1, AKR1C2, and NR4A1 overexpression, indicating altered cortisol synthesis." (PMID 38912926, 2024). "Interestingly, there were a few studies concerning AHCY37 /NCAN38 /FBP2 /GALNT339 /AKR1C2 40 and T regulatory cells/macrophages, but most of these studies contradicted with our results in immunological manners, possibly because these studies were performed in different types of tumor." (PMID 35517412, 2022). "Subsequently, we analyzed DEGs between tumor and normal tissues and selected the top five DEGs with the highest expression, which were SPP1, AKR1C2, AKR1B10, AGT, and EPHX1 in tumor tissues and NKG7, KLRD1, KLRB1, CCL5, and CST7 in normal tissues." (PMID 35967424, 2022). "AKR1B10, AKR1C1, AKR1C2 and AKR1C3 constitute some of the most inducible targets of NRF2 in human systems, both normal and tumour-derived." (PMID 27824809, 2016). "For the orthotopic xenograft model, the metastatic tumor cells, particularly the liver and bone cells, possessed significantly higher expression levels of AKR1C1, AKR1C2 and AKR1C3, corresponding with increased cisplatin resistance." (PMID 27698389, 2016). "Overall, the median level of AKR1C1, AKR1C2 and AKR1C3 was decreased in tumour, relative to normal tissue but when only mutant cases were considered, all AKRs were significantly increased." (PMID 27824809, 2016). "Expression of AKR1C1, AKR1C2, AKR7A3, CYP3A4, and CBR1 was assessed by immunoblotting in protein lysates from tumor tissue samples of the independent pretreatment set of patients." (PMID 25526449, 2014). "Indeed, this tumor expressed six of the NRF2 targets (CES1, CYP4F1, GSTM3, ARK1C1/3/4, AKR1C2, SRXN1, and PTGR1) more than 16-fold above their respective mean expressions for the entire cohort and 24 proteins more than 4-fold above their means." (PMID 37716475, 2023). "The present work demonstrates that AKR1B10, AKR1C1, AKR1C2 and AKR1C3 are transcriptional targets strongly indicative of NRF2 status in human tumours, and that NRF2 is the upstream effector of AKR overexpression in cancer, particularly in tumours of squamous origin." (PMID 27824809, 2016). "Hence, in addition to ascorbic acid, quercetin might potentiate the anti-tumor properties of BLE by down-regulating the expression of ADH4, AKR1B10 and AKR1C2, thus preventing the degradation of methylglyoxal." (PMID 27635343, 2016). "In addition, AKR1C2 expression appeared to be independent of tumor progression." (PMID 35422048, 2022). "According to GEPIA in a GBM tumor, there is also increased expression of AKR1B1, decreased expression of AKR1C1 and AKR1C2, and no change in AKR1C3 expression." (PMID 36765904, 2023).
tumor (continued). "Collectively, these results suggest that for AR negative AKR1C2 positive (AR−/AKR1C2+) ESCC, AKR1C2 mediates activation of PI3K/AKT pathway may be an alternative to DHT‐AR pathway, which uses androgen metabolites to activate a classic tumour signalling pathway." (PMID 32678482, 2020).